APOE (apolipoprotein E)
Diseases named in the same sentence as APOE in open-access papers (continued):
Sharing a sentence is not in itself a finding about the gene and the disease.
endothelial dysfunction (continued). "It reinforces that ER stress tightly correlates with endothelial dysfunction in the mesenteric arteries of ApoE KO." (PMID 29784903, 2018). "We have previously shown that low and moderate dose dietary nitrate can prevent endothelial dysfunction and improve plaque composition and stability in the ApoE−/− mouse." (PMID 30174691, 2018). "The present findings show the contribution of ER stress to the endothelial dysfunction and the effects of exercise training to reverse ER stress-mediated vascular dysfunction in mesenteric arteries of ApoE KO mice." (PMID 29784903, 2018). "When this growth factor was administered to ApoE null mice on high fat diet, endothelial cells from these mice exhibited reduced endothelial dysfunction and reduced apoptosis of primary endothelial cells." (PMID 28194400, 2017). "This latter finding was further supported by detection of increased levels of ICAM, a biomarker of endothelial dysfunction, in atherogenic–diet-fed male ApoE KO mice treated with gugulipid." (PMID 28910310, 2017). "In the previous study, administration of Ivabradine did lead to reduced endothelial dysfunction and exerted potent anti-oxidative effects in ApoE-/- mice." (PMID 28640847, 2017). "Feeding ApoE−/− mice with a high-energy diet leads to the development of atherosclerotic plaques and endothelial dysfunction." (PMID 27861612, 2016). "Considering the relationships of apolipoprotein E(ApoE) polymorphism with LDL cholesterol (LDL-C) levels and coronary risk, it is possible that it brings on susceptibility to endothelial dysfunction and atherogenesis seen on uremia." (PMID 26790728, 2016). "To avoid the effect of endothelial dysfunction in the ApoE−/− group, we studied only denuded aortic rings." (PMID 26196300, 2015). "Endothelial dysfunction has been demonstrated in the aorta of ApoE-KO mice fed a western diet and is characterized by impaired ACh-induced endothelium-mediated aortic vasodilation." (PMID 24708830, 2014). "It seems that in these ApoE−/− cells, an effort is underway to compensate for a developing endothelial dysfunction." (PMID 25344475, 2014). "In old ApoE−/− mice, endothelial dysfunction occurs but was strictly correlated with the development and size of plaques, with plaque‐free regions exhibiting normal behaviour." (PMID 25344475, 2014). "In the present study, we observed marked endothelial dysfunction in the aorta of apoE−/− mice by others in conductance and resistance vessels." (PMID 23289368, 2013). "The apolipoprotein E knockout (apoE−/−) mouse developed two decades ago, exhibits spontaneous hypercholesterolemia, accompanied by endothelial dysfunction similar to that observed in humans." (PMID 23289368, 2013). "An animal experiment shows endothelial dysfunction in cerebral arterioles were significantly increased in apoE(-/-) mice on the high-fat diet >6 months compared with the control group." (PMID 23819577, 2013). "Isolated abdominal aorta from high-fat-fed ApoE−/− mice displayed marked endothelial dysfunction compared to WT mice as sensitivity and maximum vasorelaxation responses (Rmax⁡) to the endothelium-dependent dilator ACh were significantly impaired." (PMID 23864951, 2013). "Local oxidation of circulating lipoproteins and their incorporation within the vascular endothelium, associated with oxidative processes, plays a pivotal role in the pathogenesis of endothelial dysfunction in the apoE-/- mouse." (PMID 22330242, 2012). "They showed that an increase in vascular arginase activity contributes to the mechanism of endothelial dysfunction and plaque development in the aorta of ApoE−/− mice." (PMID 22709928, 2012). "Recent evidence suggests that gender plays an important role in endothelial dysfunction in the large vessels of apoE-/- mice." (PMID 22082357, 2011).
endothelial dysfunction (continued). "There is evidence that the chemical inactivation and reduced biosynthesis of NO are the key mechanisms responsible for endothelial dysfunction in the aortas of atherosclerotic apoE-/- mice." (PMID 22082357, 2011). "In ApoE mice, endothelial dysfunction, taken as an impaired endothelium-dependent dilation, is controversial." (PMID 21586133, 2011). "Several studies provide unquestionable evidence of endothelial dysfunction in conducting and resistance vessels in the apoE-/- mouse." (PMID 22082357, 2011). "The potential of statins for the prevention and treatment of endothelial dysfunction in the apoE-/- mouse is currently under intense investigation." (PMID 22082357, 2011). "Studies of vasomotor function in the aorta of apoE-/- mice have shown that the mechanisms of endothelial dysfunction involved depletion of NO by reaction with superoxide anion radicals as well as decay of tetrahydrobiopterin by peroxynitrite." (PMID 21054825, 2010). "In contrast, female ApoE mice, even on a normal diet, show endothelial dysfunction in aorta and cerebral resistance vessels." (PMID 20482882, 2010). "Building upon this correlation, we propose a plausible mechanistic model through which endothelial dysfunction may facilitate tau pathogenesis in female APOE ε4 carriers." (PMID 41409615, 2025). "Functional characterization revealed that psEVs were sufficient to induce inflammatory endothelial dysfunction in vitro and exaggerate endothelial inflammation and atherogenesis in ApoE−/− mice, with vulnerable psEVs displaying stronger proinflammatory and proatherogenic effects." (PMID 40391195, 2025). "Based on the significant improvements in glycolipid metabolism and endothelial dysfunction after leflunomide treatment in ApoE-/- mice, it is reasonable to believe that these effects may underlie the cardiovascular protective effects of leflunomide." (PMID 39113703, 2024). "ApoE‐KO mice were fed with high fat diet for 4 weeks to induce endothelial dysfunction." (PMID 36068079, 2023). "Likewise, ApoE−/− mice were reported to develop endothelial dysfunction in both large and small blood vessels, including retinal arterioles." (PMID 37873768, 2023). "Renal proximal tubular arginase plays an important role in the kidney aging process and also contributes to vascular dysfunction in apolipoprotein E deficient mice, leading to BBB leakage and neuroinflammation, which has been associated with endothelial dysfunction in T2DM." (PMID 37047807, 2023). "Furthermore, ApoE KO mice treated with levels of L-NAME low enough to maintain normotension also exhibit endothelial dysfunction and increased atherosclerotic lesions." (PMID 38034389, 2023). "Our findings suggest that ApoE−/− mice develop endothelial dysfunction in the aorta by increased oxidative stress via the involvement of LOX-1, NOX1, and NOX2, whereas NOX4 may participate in media remodeling." (PMID 37873768, 2023). "Oral supplementation of A. muciniphila in Apolipoprotein E knockout mice (ApoE−/−) model to study the endothelial dysfunction along with atherogenesis, has shown the reduction in the metabolic endotoxemia-induced inflammatory chemokines, such as ICAM-1, MCP-1, and TNF-α on the endothelium." (PMID 36153618, 2022). "Hence, the current study investigated the effect of SeNPs stabilized with chitosan (CS-SeNPs) on inflammation and endothelial dysfunction in an early AS model of ApoE-/- mice fed with HFD for 10 weeks and in human EC line EA.hy926." (PMID 34769040, 2021).
endothelial dysfunction (continued). "Indeed, LAV-BPIFB4 gene therapy succeeded in the two primary endpoints: improving endothelial dysfunction and reducing adverse vascular effects in ApoE knockout mice." (PMID 36447743, 2021). "However, Apolipoprotein E knock-out (ApoE KO) animals have emerged as a reliable model to assess the early development of endothelial dysfunction in atherosclerotic disease." (PMID 33424633, 2020). "We recently showed that male ApoE KO rats as young as 6–9-weeks-old have greater endothelial dysfunction in their pulmonary arteries than Sprague Dawley rats after a similar simulated dive protocol (absolute pressure of 600 kPa and decompression of 50 kPa/min), due to altered NO-dependent signaling." (PMID 33424633, 2020). "Interestingly, we found that endothelial dysfunction after diving was more severe in male than in female ApoE KO rats." (PMID 31695628, 2019). "Similarly, even in diabetic ApoE‐KO mice, endothelial dysfunction was only reported in plaque‐prone regions of the aortae, while plaque‐resistant segments maintained a normal acetylcholine response." (PMID 30690853, 2019). "In addition, the ApoE −/− group also showed endothelial dysfunction, as evidenced by decreases in ACh- and SNP-induced vascular tone." (PMID 30200674, 2018). "In the present study, carotid arteries were stained to label PECAM, which confirmed that the endothelial layer remained intact for all experimental conditions, with morphological appearance of endothelial dysfunction occurring in ligated LCA of ApoE-KO mice on a chow diet." (PMID 30957020, 2018). "Various markers for inflammation, endothelial dysfunction and plaque formation are therefore of interest and in our study, we have clearly identified increased inflammatory cytokine gene expression in ApoE−/−/LDL receptor−/− testis as compared to wild-type testis." (PMID 29615651, 2018). "Previous studies have reported endothelial dysfunction in uremic apoE-/- mice fed a Western diet." (PMID 25799529, 2015). "In atherosclerotic apoE−/− mice, we then investigated the mechanism of the anti-atherosclerotic effects of xyloketal B by reducing a high degree of oxidative stress and improving impaired endothelial dysfunction." (PMID 25874925, 2015). "In ApoE−/− mice, an endothelial dysfunction, characterised by reduced ACh‐mediated relaxation, has been reported in plaque‐laden regions of the aorta, for example, in mice on a western‐style diet and in older ApoE−/− mice on a normal diet." (PMID 25344475, 2014). "Transcriptional analyses of the endothelium isolated from the aorta and skeletal muscle of these mice demonstrate reduced endothelial response to HFD, perhaps resulting from endothelial dysfunction in the preexisting hypercholesterolemic state in chow-fed ApoE(−/−)/GFP mice." (PMID 23840960, 2013). "Despite the lack of studies focusing specifically on the influence of gender on endothelial dysfunction in apoE-/- mice, there is some evidence that endothelial dysfunction in both conducting and resistance vessels is influenced by gender, aging and a Western-type diet." (PMID 22082357, 2011). "Thus, in the apoE-/- mouse, the major contribution to the endothelial dysfunction in resistance vessels appears to be from the increase in NADPH oxidase-derived •O2- and ET-1." (PMID 22082357, 2011). "Thus, the influence of female gender, associated with age and type of diet, on atherosclerotic lesions and endothelial dysfunction in the apoE-/- mouse are expected to be subject of intense research." (PMID 22082357, 2011).
endothelial dysfunction (continued). "The endothelial dysfunction was so marked that ovariectomy, which impaired the endothelial function in C57, did not cause additional damage in ApoE-deficient mice." (PMID 20482882, 2010). "Decreased SIRT1 levels and activity may lead to increased acetylation and inactivation of eNOS in the lungs of ApoE-/- mice exposed to CS culminating endothelial dysfunction." (PMID 20663150, 2010). "For example, two studies reported reduced plaque burden in the aorta after ferroptosis inhibition with Fer-1 in high fat (and high glucose)-fed ApoE−/− mice (a model that does not frequently develop IP angiogenesis), which was linked to attenuated endothelial dysfunction." (PMID 37120604, 2023). "Interestingly, vildagliptin, a DPP4i, was recently shown to inhibit the development of endothelial dysfunction and to prevent atherogenesis in non-diabetic apolipoprotein E–deficient mice." (PMID 34198786, 2021). "The experiment in high-fat fed ApoE−/− mouse model confirmed that the senescent endothelial cells accumulated in the vessels could survive through apoptosis evasion, leading to endothelial dysfunction and vascular senescence, eventually resulting in the development of vascular disease." (PMID 35187108, 2021). "Hence, our data also suggest that apolipoprotein E deficiency and endothelial dysfunction of the retinal vasculature are not deleterious to RGCs, at least in the absence of additional pathophysiological stimuli." (PMID 31781340, 2019). "The causative role of BH4 depletion in endothelial dysfunction can be demonstrated by restored endothelium-dependent dilation with overexpression of the BH4 rate-limiting enzyme, guanosine 5′-triphosphate cyclohydrolase 1 (GTPCH1) in apolipoprotein E knockout (ApoE KO) mice." (PMID 31382355, 2019). "Thus, despite some controversies, there is evidence that the apoE-/- mouse, in addition to its endothelial dysfunction, exhibits decreased VSMC responsiveness to NO in conducting arteries that have atherosclerotic lesions but not in conducting arteries that do not have atherosclerotic lesions." (PMID 22082357, 2011). "The findings that vascular endothelial cells with senescence-associated phenotypes are present in human atherosclerotic lesions and in atherosclerotic aged apoE-/- mice leads us to hypothesize that the senescence of vascular endothelial cells may be involved in endothelial dysfunction." (PMID 22082357, 2011). "The endothelial dysfunction in hypercholesterolemic animals was so marked that ovariectomy, which impaired endothelial function in C57 mice, did not cause additional vascular damage in ApoE-deficient mice." (PMID 20482882, 2010). "In the present study, the ovariectomy of female ApoE-deficient mice did not cause additional damage to the endothelial function of resistance vessels, probably because the animals already presented marked endothelial dysfunction." (PMID 20482882, 2010). "In atherosclerotic apolipoprotein E-/- (APOE-/-) mice, PVAT inflammation precedes atherosclerotic plaque formation and the development of oxidative stress and endothelial dysfunction." (PMID 35930608, 2022). "Coincident with our results, quercetin was reported to remarkably suppress endothelial dysfunction and significantly attenuate atherosclerotic lesion progression in high-fat diet (HFD)-fed ApoE−/− mice." (PMID 33425996, 2020). "Endothelial dysfunction is characterized by induction of endothelial NOS (eNOS) uncoupling, which has been observed in ApoE KO mice." (PMID 31575906, 2019). "We excluded the possibility that endothelial dysfunction was triggered by differences in IOP, blood pressure, or ocular perfusion pressure between ApoE-/- and wild-type mice." (PMID 31781340, 2019). "Unlike the aorta, the ophthalmic artery of ApoE−/− mice developed no signs of endothelial dysfunction and no signs of excessive lipid deposition." (PMID 37873768, 2023).
endothelial dysfunction (continued). "Moreover, we observed that sterol-resistant SCAP significantly increased local inflammation and induced endothelial dysfunction in the aortas of SCAPD443N mice and SCAPD443N/ApoE-/- mice." (PMID 34094640, 2021). "This suggests endothelial dysfunction at early age of ApoE KO rats although this was not studied yet." (PMID 31695628, 2019). "In turn, the early development of endothelial dysfunction in single ApoE-/- mice was not univocally accepted." (PMID 28443021, 2017). "In contrast, endothelial dysfunction in plaque free aorta segments remains unchanged in non-uremic apoE-/- mice fed standard chow." (PMID 25799529, 2015). "DHSGT treatment restored decreased PPAR-γ expression levels in the aorta of western diet-fed ApoE KO mice and the beneficial effect of DHSGT on endothelial dysfunction in diabetic atherosclerosis was similar to rosiglitazone (a PPARγ agonist) which is ameliorated in insulin sensitivity." (PMID 25280587, 2014). "Transcriptional analysis of the aortic and muscle endothelium isolated from ApoE(−/−)/Tie2-GFP mice reveals a reduced endothelial response to HFD compared to Tie2-GFP mice, perhaps resulting from preexisting endothelial dysfunction in the hypercholesterolemic state." (PMID 23840960, 2013). "Endothelial dysfunction can be detected or not in ApoE mice depending on the type of diet, age, gender, and type of vessel." (PMID 21586133, 2011). "Resistance vessels of male ApoE mice generally present normal endothelial function on a normal chow diet and endothelial dysfunction is only observed in high-fat diet conditions." (PMID 20482882, 2010). "Candidate genes reported as associated with SICH were involved in the pathways of the vessel wall integrity (ACE, APOE, neprilysin, endoglin, TGF-β1), endothelial dysfunction (ACE), inflammation markers (IL-6, TNF), and hemostasis (APOE, CD-14, Factor VII and XIII, VKORC1)." (PMID 20534169, 2010). "Since leflunomide significantly decreased plasma lipid and liver lipid accumulation in WD-fed ApoE-/- mice and FFA-stimulated AML12 cells, we thus investigated whether leflunomide and teriflunomide ameliorates endothelial dysfunction and protects vascular function in vitro and in vivo." (PMID 39113703, 2024). "have reported that endothelial dysfunction was improved with the reduction of A. muciniphila abundance in ApoE−/− mice and suggested the reason for the negative role of A. muciniphila could be due to an individual’s health and microbiota pattern." (PMID 36153618, 2022). "In an ApoE knockout mice fed a high-lipid diet, a well-known atherosclerosisprone murine model, it has been demonstrated the efficacy of LAV-BPIFB4 in contrasting endothelial dysfunction, plaque progression, inflammatory cytokine release, macrophage shift, and T cell activation." (PMID 36447743, 2021). "Although the retinal vasculature supplies the inner retinal layers, including the RGC layer, the mice displayed a normal RGC number, suggesting that redundant mechanisms exist in the inner retina to compensate for the lack of ApoE and for endothelial dysfunction." (PMID 32824523, 2020). "Interestingly, in ECs of adult ApoE−/− mice, which have endothelial dysfunction but do not develop plaques, cilia are expressed ectopically in the common carotid artery despite the presence of laminar flow, compared to wildtype mice that are devoid of cilia." (PMID 31344780, 2019). "Interestingly, other previous studies in ApoE-/- mice revealed that some small blood vessels do not develop endothelial dysfunction." (PMID 31781340, 2019).